ALB (albumin)
Diseases named in the same sentence as ALB in open-access papers (continued):
Sharing a sentence is not in itself a finding about the gene and the disease.
adenocarcinoma (23 papers, 2002 to 2025). A common cancer characterized by the presence of malignant glandular cells. "Specifically, higher levels of Albumin were associated with a reduced risk of adenocarcinoma (OR = 0.599, 95% CI: 0.369–0.974, P = 0.039)." (PMID 40719999, 2025). "Higher albumin levels were associated with reduced adenocarcinoma risk (OR = 0.599, 95%CI: 0.369–0.974, P = 0.039)." (PMID 40719999, 2025). "Similarly, the C-reactive protein–ALB ratio is strongly associated with poor prognosis in patients with adenocarcinoma of the esophagogastric junction and upper GC." (PMID 40601671, 2025). "The protective effect of Albumin against adenocarcinoma risk observed in our study may be due to its role in buffering OS and maintaining cellular homeostasis." (PMID 40719999, 2025). "An increase in the magnitude of the systemic inflammatory response was associated with an increase in the relative proportion of non-adenocarcinoma (P=0.014), increased weight loss (P=0.004), reduced haemoglobin (P<0.001) and albumin concentrations (P<0.001) and reduced performance status (P=0.060)." (PMID 12177792, 2002). "Logistic regression revealed that adenocarcinoma type, systemic infection, elevated D-dimer, and low albumin were significant predictors of PE recurrence." (PMID 41200633, 2025). "To find the possible predictors for mortality, we employed multivariable logistic regression analysis, and the results revealed two independent predictors: adenocarcinoma and low serum albumin." (PMID 41200633, 2025). "For example, researchers have developed a new prognostic score for adenocarcinoma of the jugular abdominal region according to the preoperative ratio of total bilirubin-albumin and fibrinogen-albumin by using a controlled study approach." (PMID 40291905, 2025). "However, in our study, this association did not remain significant in the multivariable logistic regression, where adenocarcinoma histology, systemic infection, low serum albumin, and elevated D-dimer were identified as independent predictors." (PMID 41200633, 2025). "Adenocarcinoma, which is often associated with environmental and genetic factors such as smoking and mutations in EGFR and ALK genes, may be more susceptible to the protective effects of Albumin, which helps maintain cellular integrity in the presence of OS." (PMID 40719999, 2025). "The combination of camrelizumab, albumin-bound paclitaxel, and S-1 as first-line treatment for patients with HER2-negative advanced G/GEJ adenocarcinoma showed promising efficacy and an acceptable safety profile." (PMID 41550955, 2025). "Clinical variables statistically associated with both better PFS and OS, were clinical stage, adenocarcinoma histology, ECOG 0–1, number and site of metastasis and plasma albumin levels." (PMID 36624406, 2023). "Clinical variables associated with overall survival (OS) in NSCLC patients were clinical stage, adenocarcinoma histology, Eastern Cooperative Oncology Group (ECOG), number and site of metastasis, plasma albumin levels and first-line treatment with platinum." (PMID 36624406, 2023). "INS, TOP2A, ACACA, ALB, and TXN are the key genes which play an important role in adenocarcinoma." (PMID 30425814, 2018).
gastrointestinal tumors (23 papers, 2015 to 2025). "As early as 1984, Japanese scholars first proposed PNI to evaluate the perioperative condition of patients with gastrointestinal tumors and predict the operation risk by combining albumin and the total number of lymphocytes in peripheral blood." (PMID 37197434, 2023). "However, in advanced gastrointestinal tumors, there is often insufficient intake and excessive loss, leading to a decrease in albumin levels and an increase in perioperative risk, further affects clinical outcomes." (PMID 37554699, 2023). "In fact, low serum albumin is associated with poor prognosis in gastrointestinal tumors." (PMID 35729545, 2022). "Single markers of fibrinogen and pre-albumin are limited and unstable in predicting the prognosis of digestive system tumors." (PMID 35033080, 2022). "GPS is an inflammation biomarker based on CRP and ALB, which has been shown highly discussed in gastrointestinal tumors including ESCC before." (PMID 34315926, 2021). "We identified laboratory tests (haemoglobin, albumin, and CAR), Oakland score (points ≥12), and histopathological findings (fibrin thrombi) in patients with LGIB caused by colon ischaemia." (PMID 34726101, 2021). "Previous studies have also combined different indicators, such as the number of metastatic sites, gastrointestinal tumors, PS score, age, platelet, neutrophil, absolute lymphocyte counts, LDH, ALB and NLR, and so on to form a new prognostic scoring system." (PMID 36059799, 2022). "Age, Dukes’ stage, albumin, carcinoembryonic antigen (CEA) and the Glasgow Prognostic Score were amongst those in gastrointestinal tumors." (PMID 26717416, 2015).
psychiatric disorder (19 papers, 2012 to 2025). A disorder characterized by behavioral and/or psychological abnormalities, often accompanied by physical symptoms. "Univariate regression identified age, stage classification (I/II vs. III/IV), ECOG-PS (0-1 vs. 2-4), psychiatric disorder, and albumin level as factors significantly associated with BSC (p<0.0001)." (PMID 40909092, 2025). "This study identified advanced age, stage classification, presence of psychiatric disorders, and low serum albumin levels as significant risk factors associated with the selection of BSC as the initial treatment strategy." (PMID 40909092, 2025). "Univariate regression identified stage classification (I/II vs. III/IV), ECOG-PS (0-1 vs. 2-4), psychiatric disorder, and albumin level as significant factors associated with BSC (p<0.001)." (PMID 40909092, 2025). "Albumin has antioxidant properties, and previous research reported that higher levels of this molecule are associated with a better prognosis of psychiatric disorders." (PMID 38541067, 2024). "Two CIRS-G–specific domains, namely respiratory and psychiatric diseases, and low albumin level were independently associated with functional decline (model 2)." (PMID 33121435, 2020). "Multivariate analysis revealed that age, stage classification, psychiatric disorder, and albumin level were more significant factors of BSC." (PMID 40909092, 2025). "Further longitudinal prospective studies with larger sample sizes are required to confirm the role of ALB level in predicting cognitive function in patients with psychiatric disorders." (PMID 39696133, 2024). "Both TP levels and albumin/globulin ratio in patients with psychiatric disorders have been reported to be significantly aberrant by detecting the sample of 278 spinal fluids." (PMID 35958662, 2022). "Albumin is also a marker that contributes to inflammation in the immune system, which has been proven in the pathogenesis of psychiatric disorders." (PMID 35883877, 2022). "Age (OR: 1.20, 95% CI: 1.10-1.36; p=0.0008), stage classification (I/II vs. III/IV) (OR: 13.79, 95% CI: 2.34-137.75; p=0.0026), psychiatric disorder (OR: 8.73, 95% CI: 2.34-137.75; p=0.021), albumin level (OR: 0.03, 95% CI: 0.002-0.24; p=0.003) were factors in BSC." (PMID 40909092, 2025). "There are studies examining the role of serum albumin levels in patients with psychiatric diseases." (PMID 38248795, 2024).
gastrointestinal disease (17 papers, 2013 to 2025). A disease that occurs in the gastrointestinal system, excluding the hepatobiliary system. "One dog showed mild abnormalities on hematology and serum biochemistry, linked to gastro-intestinal disease (low albumin, elevated ALP, ALT, and GLDH)." (PMID 39846019, 2024). "The univariate regression analysis showed 10 variables with P-value less than 0.05, including old age, BMI, accompanying T2DM and gastrointestinal disease, preoperative albumin, the ratio of albumin to globulin, prealbumin, blood loss, operative time, and stage of fusion." (PMID 34717707, 2021). "Fourth, we had excluded patients with severe liver pathology and gastrointestinal disease, which leaded to losses of serum albumin." (PMID 40785303, 2025). "When used in tandem, serum albumin <3.5 g/dL and body weight <325 g identified 100% of the marmosets affected with concurrent bone and gastrointestinal disease." (PMID 24324827, 2013). "Twenty adult horses, ≥ 1 year of age, were prospectively enrolled, with informed client consent, if they developed acute hypoproteinemia, defined as a plasma total protein <5.0 g/dL or albumin <2.2 g/dL during hospitalization while undergoing treatment for gastrointestinal disease." (PMID 25237987, 2014). "The lack of association did not change when stratifying the population by baseline albumin, creatinine or the presence of gastrointestinal disease (data not shown)." (PMID 23806101, 2013).
endocrine disease (11 papers, 2014 to 2025). "Interestingly, this network focused on the three major DKD-associated ‘diseases and functions’ relevant to our study—endocrine system disorders, renal tubule injury, and decreased levels of albumin." (PMID 36934129, 2023). "The key challenges were managing septic complications and critical illness-induced endocrinopathies, monitoring fluid balance and albumin levels, especially with ongoing inflammatory losses and possible multiorgan failure." (PMID 40941429, 2025). "Among patients presenting with elevated IL-6, endocrinopathy, higher free light chains, lower serum albumin, ascites, hepatomegaly and abnormal DLCO were all more common." (PMID 40646134, 2025). "The observations pointed to endocrine system disorders, renal tubule injury, and decreased levels of albumin as the enriched ‘diseases and functions’." (PMID 36934129, 2023). "The genes from these pathways were constructed into a topological network, which when overlaid with the ‘diseases and functions’ module revealed endocrine system disorders, renal tubular injury, and decreased levels of albumin as relevant functions during DKD." (PMID 36934129, 2023). "A notable improvement was seen following 4 months of therapy, as evidenced by normalization of CRP, hemoglobin, albumin, renal function, and resolution of his endocrinopathy." (PMID 31453020, 2019). "We observed that lethargy, anorexia, albumin, and sodium may support an increase in the suspicion of this endocrine disease." (PMID 39764376, 2024).
connective tissue disease (10 papers, 2006 to 2024). "In the adjusted cohort, the adjustment variables—including age, sex, hospital, presence of malignancies, interstitial pneumonia or connective tissue disease, serum albumin, lactate dehydrogenase, serum creatinine clearance, and respiratory status—were well balanced, with SMD values below 0.1." (PMID 39488718, 2024).
digestive system cancer (9 papers, 2010 to 2025). A primary or metastatic malignant neoplasm involving any part of the digestive system. "In a meta-analysis examining studies on the cancer of the gastrointestinal tract, 26 of 29 studies reported that higher serum albumin levels were associated with prolonged survival." (PMID 35847924, 2022). "Of the 29 studies reviewed on cancers of the gastrointestinal tract, all except three found higher serum albumin levels to be associated with better survival in multivariate analysis." (PMID 21176210, 2010). "We also found that lower levels of serum uric acid and albumin, as well as higher levels of AST/ALT ratio were associated with digestive system cancers." (PMID 40597094, 2025). "The prognostic nutritional index (PNI), calculated using albumin and lymphocyte counts in the serum, is an effective prognostic factor for various malignancies, especially digestive system carcinomas." (PMID 38438901, 2024). "Previous studies have shown that the albumin-to-globulin ratio (AGR) is an independent prognostic factor in digestive system cancers, such as colorectal cancer, gastric cancer, and cholangiocarcinoma." (PMID 36983238, 2023). "The albumin/globulin ratio (AGR) has been widely reported to be a potential predictor of prognosis in digestive system cancers (DSCs), but convincing conclusions have not been made." (PMID 29300750, 2018).
brain disease (7 papers, 2020 to 2025). "Current diagnosis of brain disease in dogs is dependent on imaging and cerebrospinal fluid (CSF) analysis, including total nucleated cell counts and albumin concentrations." (PMID 40859633, 2025). "FITC–albumin has been used to evaluate the BBB permeability for brain diseases." (PMID 32076591, 2020). "Red blood cell distribution width-to-albumin ratio (RAR) is a combined new indicator reflecting immunology and has been reported to predict the prognosis of inflammation-related diseases and brain diseases." (PMID 38274889, 2023).
electrolyte imbalance (7 papers, 2011 to 2023). "Elevation of the anion gap, a measure of electrical neutrality, corresponds well with electrolyte imbalance, as well as marked alterations in albumin and lactate." (PMID 34095283, 2021). "We measured total 25(OH)D, DBP, and serum albumin levels in 49 healthy young adults enrolled in the Metabolic Abnormalities in College-Aged Students (MACS) study." (PMID 21416506, 2011).
digestive diseases (6 papers, 2021 to 2025). "Patients with high preoperative sleep quality, high preoperative albumin level, free of digestive disease and undergoing THA procedure are more likely to be discharged within 2 days." (PMID 35855669, 2022). "Patients with high sleep quality, with high preoperative albumin, without digestive diseases and undergoing THA are more likely to discharge within 2 days after surgery." (PMID 35855669, 2022).
hematological cancer (6 papers, 2019 to 2023). "In hematologic cancers, albumin has also been shown to be a strong predictor of prognosis and is one of the factors in the ISS." (PMID 36441260, 2023).
benign tumor (5 papers, 2017 to 2025). "The correlation between reduced albumin levels and prolonged hospitalization applied to the entire sample and to almost all hospital wards (except for gynecology and obstetrics), and also to certain diseases like benign tumors and inflammatory diseases." (PMID 28344803, 2017). "The most important features distinguishing the four HCM subtypes determined are: LDH, AO, AOvs, PLWd, LVOT Vmax, MVmeanPG, MVmaxPG, Peak VE/VCO2, presence of heart murmur, AV maxPG, AscAO, AscAO, HCM in family history, serum albumin, weight, LVOT maxPG, MVVTI, AV meanPG, and RVSP." (PMID 36294999, 2022). "Low levels of albumin were not related to increased length of stay only in benign tumors and inflammatory diseases." (PMID 28344803, 2017).
head and neck tumors (5 papers, 2023 to 2025). "Particularly in the group of head and neck tumors, parameters were identified that showed an association with PFS: Leukocyte, neutrophil, and CRP-albumin ratio values above the median were associated with shorter PFS." (PMID 41361351, 2025). "As non-head and neck tumors are highly vascular and upregulate numerous serum proteins, it is likely that these tumors leak proteins such as IgG and albumin from the serum into the oral rinse samples, thus raising solCD44 levels." (PMID 39030509, 2024). "Because most of our patients had advanced-stage malignant head and neck tumor, many of them had low albumin levels preoperatively." (PMID 37629355, 2023). "Xu found in 315 patients with head and neck tumors that perioperative serum albumin supplementation positively influenced the occurrence of surgery-related local complications (6.5% vs. 21.6%) associated with head and neck free flaps, as well as length of hospital stay." (PMID 37629355, 2023). "Moreover, patients with large head and neck tumours have higher serum levels of proinflammatory and proangiogenic cytokines 48, which may lead to a low serum ALB concentration 49 and, in turn, a low AGR." (PMID 36741261, 2023).
blood cancer (4 papers, 2021 to 2024). "Thus, our analysis of the optical and electrochemical characteristics of Ag thin films and Ag nanosquare arrays showed that both can be used as an alternative biomedical technology to monitor the prognosis of blood cancer based on the concentration of serum albumin in blood." (PMID 34835873, 2021). "Therefore, the actualization of an Ag nanosquare array electrode and an Ag thin film electrode is proof that both Ag nanosquare arrays and Ag thin films can be used to monitor the prognosis of blood cancer based on the concentration of serum albumin using spectroscopic and electrochemical methods." (PMID 34835873, 2021).
genetic diseases (4 papers, 2023 to 2025). "We used evoCAST to install human factor IX cDNA into ALB intron 1; to insert a CD19-targeted chimeric antigen receptor into TRAC; and to integrate wild-type cDNAs of four genes implicated in loss-of-function genetic diseases into intron 1 of their respective endogenous loci." (PMID 40373119, 2025).
central nervous system diseases (2 papers, 2019 to 2022). "DHF is a promising candidate in the treatment of central nervous system diseases; however, its possible pharmacokinetic interactions with serum albumin and biotransformation enzymes have not been characterized." (PMID 31731555, 2019).
inflammatory myopathy (2 papers, 2024 to 2025). "The albumin, total protein, and HDL cholesterol levels were not significantly different between broilers with and without dorsal cranial myopathy." (PMID 38791716, 2024).
autosomal dominant disease (1 paper, 2020). Autosomal dominant form of disease. "It is a familial autosomal dominant disease caused by a mutation in the albumin gene, leading to the structural modification of albumin and an increased affinity between albumin and thyroxine." (PMID 33329389, 2020).
bone disorder (1 paper, 2019). "Thus, serum albumin measurement should be considered in determining bone disorders among these patients." (PMID 31839746, 2019).
ALB also shares sentences with these, for which no sentence is quoted: portal hypertension (132 papers); acute myocardial infarction (58); Glomerular sclerosis (26); acute respiratory failure (19); dialysis (12); gallbladder cancer (11); gingivitis (9); Coma (8); alcoholic fatty liver disease (7); chronic periodontitis (7); cognitive disorder (7); cor pulmonale (7); intestinal disease (7); chronic bronchitis (6); Mitral regurgitation (6); aspergillosis (5); cardiac arrhythmia (5); Hepatomegaly (5); Hypoinsulinemia (5); Hypovolemia (5); pituitary adenomas (5); polyneuropathy (5); adenovirus infection (4); Adrenocortical Carcinoma (4); autosomal dominant polycystic kidney disease (4); diverticular disease (4); hemolysis (4); hepatopulmonary syndrome (4); hypertrophic cardiomyopathy (4); hypotension (4).
A further 447 diseases each share a sentence with ALB in 4 papers or fewer.